IL5 (interleukin 5)
Diseases named in the same sentence as IL5 in open-access papers (continued):
Sharing a sentence is not in itself a finding about the gene and the disease.
inflammation (continued). "Furthermore, eMOD prevented the development of airway inflammation, as demonstrated by attenuation of bronchoalveolar lavages eosinophil influx, peribronchial inflammatory infiltrate, and mucus secretion in lungs and IL-4 and IL-5 levels in lung cell cultures." (PMID 23844022, 2013). "We evaluated the gene-based expression of type 2 cytokines (IL-4, IL-5, and IL-13) and STAT 6, which is a transcription factor that plays a crucial role in the pathogenesis of allergen-induced airway inflammation." (PMID 38790633, 2024). "The degree of nasal mucosal inflammation in AEO group improved, the levels of immunoglobulin E (IgE), histamine, IL-4, IL-5, IL-17 were decreased, and the level of IFN-γ was increased obviously with EC50 = 2 g/kg." (PMID 32395767, 2020). "Pro-inflammatory cytokines such as IL-1α, IL-1β, IL-2, IL-5, IL-6, IFN-γ, MCP-1, MIP-1α, MIP-1β and TNF-α are shown to play an essential role in inducing age-related chronic inflammation." (PMID 31181695, 2019). "Furthermore, the IL-17RB and ST2 expressions on mDCs were also correlated with the IL-5 mRNA level and eosinophil numbers in NP tissues, suggesting that mDCs might play a role in IL-25- and IL-33-induced type 2 responses and eosinophilic inflammation in NP." (PMID 30519393, 2018). "Treating mice with TRX inhibits the development of airway inflammation and the overproduction of macrophage inflammatory protein (MIP)-1, RANTES, IL-4, and IL-5, which are responsible for the development of allergic inflammatory responses." (PMID 30469393, 2018). "Loss of both IL-4 and IL-5 during OVA-induced airway inflammation did not abolish airway hyperreactivity, which was abolished only after anti-CD4 treatment, suggesting that ST2/IL-33 signaling in CD4 T cells may be critical for efficient antigen-induced airway inflammation." (PMID 28484466, 2017). "Eosinophil: granular leukocytes that are recruited to the lung by IL-5 and C-C chemokines (CCL11, CCL24 and CCL26) to mediate allergen-induced airway inflammation." (PMID 23828644, 2013). "The result of the OVA-induced airway inflammation model shows that Th2 suppression in BALF evaluating IL-4 and IL-5 cytokine production both in preventive and therapeutic administration is possible by delivering an antigen to the cell surface by mRNA-LNP technology." (PMID 41007857, 2025). "Interleukin-5 (IL-5) contributes to eosinophil activation, while interleukin-17 (IL-17) and interferon-gamma (IFN-γ) from T-helper 1 (Th1) and T-helper 17 (Th17) cells drive chronic inflammation and further damage to the skin." (PMID 40161158, 2025). "In the asthmatic mice induced by sensitization and provocation of airway inflammation with OVA, production of IL-4 and IL-5 in the BALF and inflammatory cells such as leukocytes, neutrophils, lymphocytes, monocytes, eosinophils, and basophils were increased, which enhanced AHR." (PMID 30545126, 2018). "Along with the reduced eosinophilic airway inflammation, IL-13 levels in BALF tended to be lower in OLA-pretreated mice and the production of IL-4 and IL-5 was significantly reduced in BP-restimulated lung cells of OLA-pretreated mice compared to sensitised controls." (PMID 27149118, 2016). "Transfer of WT pDCs also limited RV-induced AHR, eosinophilic airways inflammation and production of IL-5 and CCL11 but not IL-13 release." (PMID 26108570, 2015). "With regard to OVA-induced airway inflammation, we demonstrated that the magnitude of immune response with respect to goblet cell hyperplasia, airway reactivity, BAL fluid IL-5, IL-10 and serum OVA-specific IgE production is significantly lower in C57BL/6 mice than in BALB/c." (PMID 19438585, 2009). "Moreover, the concomitant thoracic trauma induced pulmonary inflammation, indicated by lung damage, increased inflammatory mediators in the BAL fluids, including IL-6, IL-5, eotaxin, MCP-3, and MCP-1, and increased neutrophil infiltration into the lungs in mast cell-competent mice." (PMID 35558068, 2022).
inflammation (continued). "Besides, the correlations between BIRC3 expression and asthmatic eosinophilic/allergic inflammation indicators (FeNO, IgE, and EOS%), pulmonary function (FEV1, FEV1% pred, FVC% pred, and FEV1/FVC), and inflammatory cytokines (IL-4, IL-5, IL-13, IL-25, IL-10, IL-33, and TSLP) were analyzed." (PMID 35287655, 2022).
cancer (90 papers, 2006 to 2026). A tumor composed of atypical neoplastic, often pleomorphic cells that invade other tissues. "Additional candidate drivers in fBM following maternal OM-85 treatment included CD38, IL5, and an array of microRNAs (miR) recognized principally in the context of cancer-associated functions." (PMID 33424847, 2020). "The link between the deficiency of immune system and cancer has been well established, and here it is evident by the statistical significance in immunology related pathways, such as IL-5 pathway (combined P = 0.0105)." (PMID 27409342, 2016). "Furthermore, IL-5 directly recruits and activates mature eosinophils, and both IL-5 and eosinophils have been implicated in cancer." (PMID 37455828, 2023). "Associations with IL-5 and cancer-related fatigue have previously been described clinically." (PMID 27893434, 2017). "Specifically, we observed a significant decrease in the levels of MIP-1α, GM-CSF, IL-13, IL-6, IL-10, IL-5, IL-12p70, and IL-4 after SNS administration, all of which are associated with the severity of MMD symptoms and cancer prognosis." (PMID 41491244, 2026). "Theoretical risks of depleting eosinophils through IL-5 blockade include impaired host defense against certain infections, especially parasites and helminths, as well as potential roles in cancer defense." (PMID 40726873, 2025). "Univariate analyses revealed that factors with a significant role in HCC risk prediction in the two biological compartments are two cytokines, IL-5 and IL-15, previously found to play a controversial role in cancer pathogenesis." (PMID 37686245, 2023). "PaTu8988T amoeboid cells were shown to secrete high levels of interleukins [such as interleukin-1α (IL-1α), IL-5, IL-6, IL-7, IL-8, and IL-9], as well as several chemokines involved in cancer progression." (PMID 37851808, 2023). "In both cancer patients and non-cancer-afflicted subjects, IL-4, IL-5, IL-12p70, IL-17, IFN-α, and TNF-α all trended to significantly decrease at the early stage and markedly increase at the late stage of Omicron infection." (PMID 37035158, 2023). "It has been suggested that lung group 2 innate lymphoid cells (ILC2), which produce IL-5 or IL-13 in response to IL-25 and IL-33, suppress the lung metastasis of cancer cells." (PMID 34170380, 2022). "The results of PPI demonstrated that the five TFs were tightly associated with many critical cancer related factors or pathways, such as SMAD4, MMP13, IL-5, IL-2, CYP2E1, CCNE1 and CDH1." (PMID 34405021, 2021). "While IL-4, IL-5 and IL-13 have been documented to contribute to cancer growth and metastasis, a dual pro- and anti-tumorigenic role of IL-10 has been reported in recent literature, as reviewed elsewhere." (PMID 34012451, 2021). "This high IL-5 protein expression was significantly detected in moderately differentiated (68.4%) and poorly differentiated (63.6%) carcinomas compared to well differentiated ones (22.2%) (p = 0.004)." (PMID 34744521, 2021). "IL5-mediated signaling and Syndecan-1-mediated signaling enhances cancer cell migration and invasion." (PMID 32448176, 2020). "Metastasis of cancer cells is closely associated with angiogenesis stimulated by angiogenic activators such as PDGF-BB, TGF-β1, FGF, HGF, NOS, COX-2, IL-5, and VEGF." (PMID 30949393, 2019). "The results of this review show that açaí acts in the inflammatory processes involved in induced-cancer in animals by decreasing the levels of IL-1β, IL-5, IL-6, IL-8, COX-2, TNF-α and MPO and increasing the levels of IFN-γ." (PMID 29966007, 2018). "A-ME/CFS subjects who developed malignancies (n=8) had higher levels of IL5, CSF2 and PDGFBB than other A-ME/CFS subjects." (PMID 28375204, 2017). "The binding of IL-5 to IL-5Rα receptor induces the migration of cancer cells was reported, and corresponding genes showed significant results in our GWAS analysis." (PMID 27409342, 2016).
cancer (continued). "Mast cells play a key role in the pathogenesis of cardiovascular diseasesand cancers via secreting a variety of cytokines includingTNF-α, IL-3, IL-4, IL-5, IL-6, IL-10, IL-13, IL-14 and IL-16." (PMID 26625310, 2016). "The importance of IL-5 is justifiable since previous studies showed that IL-5 enhanced cancer invasion and migration." (PMID 27409342, 2016). "Another 2 cytokines changed but instead of finding an increase in IL-5 and IL-12 (p40), they were significantly decreased with cancer (CA2) compared to their levels in the serum of the control mice (PBS2)." (PMID 26113869, 2015). "Treatment of both types of cancer cells with IL-5 resulted in significant up-regulation of MMP-9 expression in a concentration- and time-dependent manner, detected using gelatin zymography and immunoblot analysis." (PMID 22962576, 2012). "Increased Th2 cells promote cancer growth and metastasis by producing IL-4, IL-5, and IL-10." (PMID 38293522, 2024). "Furthermore, there are few studies that directly assessed the expression of IL-5, IL-9, or their receptors in human cancer." (PMID 37455828, 2023). "In addition, it’s well known that Th2 cells contribute to cancer progression and metastasis by secreting IL-4, IL-5, IL-10 and IL-13." (PMID 37950236, 2023). "Therapeutic targeting of IL-33 or IL-5 reversed NK cell suppression and impaired cancer burden." (PMID 33233582, 2020). "However, it is found that the classical type 2 immune cytokines IL-4, IL-5, IL-9, and IL-13 may have conflicting roles in cancer." (PMID 37455828, 2023). "Therefore, obese cancer patients with increased neutrophilia, GM-CSF or IL-5, may benefit from anti-IL-5 therapies to prevent lung metastasis development." (PMID 33339340, 2020). "The secretion of IL-2, IL-5, IL-8, MCP-1, and VEGFA was significantly reduced in both the sh-MMP28-1 and sh-MMP28-2 AsPC-1 and BxPC-3 cancer cell lines." (PMID 39972459, 2025). "Cytokine antibody array analysis revealed that MMP28 knockdown suppressed the production and release of IL-2, IL-5, IL-8, MCP-1, and VEGFA by cancer cells." (PMID 39972459, 2025). "KEGG analysis identified adhesion, hematopoiesis and cancer-related proteoglycans as affected pathways (e.g. metformin: CD9, CTSL, IL5, HGF; insulin: EGF, EZR, PLCG2, TFRC)." (PMID 33690729, 2021). "CD4+ T cell subsets, such as Th1, Th2, Th17, and regulatory T (Treg) cells, serve pivotal functions in cancer immunity, among which the Th2 subset of CD4+ T cells secretes IL-4, IL-5, and IL-13, and activates B cells to become antibody-secreting plasma cells." (PMID 35069553, 2021). "The up‐regulation of IL‐4, IL‐5 and IL‐10 as seen in our MRMT‐1/Luc2‐bearing animals is in agreement with previous data and is indicative for cancer physiology modulation." (PMID 31724155, 2021). "We recently reported IL-5, IL-10, IL-6, CxCL-10, and TGF-β elevation in both participants with EpKS and EnKS when compared to KSHV-infected asymptomatic controls prior to cancer therapy." (PMID 32560243, 2020). "Serum of mice that had received cancer cells secreting IL-15sol showed significantly elevated levels for Eotaxin, G-CSF, IFN-γ, IL-1α, IL-5, IL-6, IP-10, KC, MCP-1 and MIG." (PMID 31856922, 2019). "We further included the 9 known cancer-signaling pathways from the NetPath database, namely, EGFR1, FSH, IL-1, IL-4, IL-5, Leptin, RANKL, TNF-alpha, and TSH." (PMID 29190299, 2017). "As typical examples, b-FGF, IL-9, IP-10, RANTES, and G-CSF were higher in supernatant of CSCs culturing, while TGF-β1, TGF-β3, IL-5, IL-12, and PDGF-BB were higher in supernatant of cancer cells culturing." (PMID 25118635, 2014).
cancer (continued). "In the cancer setting, the primary readout is IFNg, secreted by CD8+ T cells and Th1 cells, but inclusion of IL-5 as a second cytokine comes with only minor additional costs in the Fluorospot assay and can provide insights on the presence of epitope specific Th2 cells." (PMID 40103827, 2025). "There is no doubt that IL-5 is a cytokine involved in the pathogenesis of allergic inflammatory responses; however, its role in cancer processes remains poorly understood." (PMID 40143164, 2025). "Other immunotherapeutic strategies under study for MSI-H cancers include vaccines, systemic immunomodulators, STING agonists, PKM2 activators, T-cell immunotherapy, LAIR-1 immunosuppression reversal, IL5 superagonists, oncolytic viruses and IL12 partial agonists." (PMID 38254772, 2024). "The higher the Log IL5, the lower the FACT-PCI in the non-cancer and pre-C/T subgroups." (PMID 34073990, 2021). "It is possible that IL5-driven immune surveillance targets more strongly against ER positive cancer cells and thus the higher ratio of ER negative vs. ER positive odds in patients with high IL5 levels." (PMID 24473087, 2014). "Like other cytotoxic cancer therapies, immunotherapy promotes inflammation within the TME, which can include cytokine release syndrome characterized by hypersecretion of pro-inflammatory cytokines, including IL-6, IL-1, TNFα, IL-5, IL-10, IFN, and TGFs by various immune cells." (PMID 38330013, 2024). "Similar to IL-4, currently there are no ongoing clinical trials involving IL-5 or IL-9 in cancer treatment, likely a reflection of our current inadequate understanding of whether they would promote or inhibit cancer under different contexts." (PMID 37455828, 2023). "Seven pathways, including the Androgen receptor, Hedgehog, IL-1, IL-5, IL-9, Notch, and Wnt signaling pathways were not significantly perturbed by any condition in our dataset, leaving 13 pathways that were perturbed by at least one cancer." (PMID 22536907, 2012). "Consistent with international consensus for cachexia diagnosis, our results demonstrate systemic inflammation in cancer cachectic vs. non-cachectic patients, with increased circulating CRP, IL6, TNFα, IL8, and IL5 levels." (PMID 28288584, 2017).
bacterial infection (20 papers, 2012 to 2025). "S100A8/9 and IL5 were the most significantly increased and decreased proteins, respectively, in the bacterial infection category." (PMID 37831367, 2024). "Additionally, post-bacterial infection, the expression of IL-5 was notably decreased compared to the control group (p < 0.05)." (PMID 40136393, 2025). "Additionally, it is also noteworthy that HPV infection modulates the immunological response towards a predominance of Th2-type response (IL-4, IL-5, IL-10, and IL-13), which favors persistence of bacterial infection." (PMID 36897879, 2023). "However, pDCs induced a prominent Th2-like profile compared with CD11c+ DCs (higher secretion of IL-4, IL-5, and IL-10), suggesting different contributions to immune regulation in the context of bacterial infection." (PMID 31017904, 2019). "Interestingly, non-eosinophilic exacerbations triggered by viral or bacterial infections were observed in patients treated with mepolizumab, an anti-IL-5 antibody, suggesting that removal of eosinophils may cause expansion of virus and/or bacteria." (PMID 40083723, 2025). "Angiopoietin 4 (ANGP4), CD9, and immunoglobulin E (IgE) were increased and LFA3, IL5, and CD45RB were among the most decreased proteins in bacterial infection." (PMID 37831367, 2024). "Cytokines such as IL‐1β, IL‐2, IL‐5, IL‐6, IL‐8, IL‐12p70, IL‐17, and TNF‐α may be involved in the progression of COVID‐19 combined with bacterial infection." (PMID 39692539, 2024). "Serum cytokines including IL‐1β, IL‐2, IL‐5, IL‐6, IL‐8, IL‐12 p70, IL‐17, and TNF‐α were significantly higher in COVID‐19 patients with bacterial coinfections than those without bacterial infection." (PMID 39692539, 2024).
immune disease (18 papers, 2005 to 2025). "Preparations from Hericium coralloides and T. versicolor rebalanced cytokine profiles in immune cells from older adults, reducing IL-5 and IL-13 while adjusting IL-1β, IL-6, and interferon levels—an effect relevant to age-related immune dysfunction." (PMID 41488566, 2025). "CD is characterized as a Th1-mediated inflammatory response with overproduction of interferon-γ (IFN-γ) and TNF-α whereas UC is considered a Th2-mediated immune disease with massive production of interleukin IL-4, IL-5, IL-9, and IL-13." (PMID 30150894, 2018). "In the current study, upregulation of c-Maf, GATA3, IL-5, and IL-13 in the colonic mucosa of HES goats confirmed that the colonic inflammation in growing goats caused by HES was attributed to the TH2 cytokine pattern, which might be related to the TH2-mediated immune disorder." (PMID 38395946, 2024). "UC is a TH2 type immune disease, with up-regulation of IL-5, whereas CD is a TH1 type immune disease, showing high levels of interferon gamma (IFN-), IL-12, and tumor necrosis factor alpha (TNF-α)." (PMID 32851982, 2021). "It is well known that IFN-γ, IL-4/IL-5/IL-13 and IL-17 are pro-inflammatory cytokines expressed or secreted by activated Th1, Th2 and TH17 cells, respectively, and play key roles in various immune diseases." (PMID 38664707, 2024). "Altogether, our data indicate elevated contents of inflammatory cytokines TNF-α, IL-4, IL-21, BAFF, IL-31, IL-5 and APRIL in CSF samples from ASD patients, suggesting the potential inflammatory conditions and immune dysfunctions that might contribute the pathogenesis and progression of this disease." (PMID 38114596, 2023).
respiratory disease (17 papers, 2013 to 2025). "However, the induction of TH2 cytokines such as IL-4, IL-5 and IL-13 has been associated with vaccine-associated enhanced respiratory disease (VAERD), a set of diseases with predominant involvement of the lower respiratory tract." (PMID 35287350, 2022). "Several biological products are being studied for use in respiratory diseases, such as anti-IgE (omalizumab), anti-IL-5 (mepolizumab, reslizumab, benralizumab), anti-IL-4, and anti-IL-13 (dupilumab), among others." (PMID 38367543, 2024). "The induction of CD4+ type 2 helper T-cell (Th2) (IL4, IL5, or IL13) responses has been associated with vaccine-associated enhanced respiratory disease (VAERD), as seen in some patients with respiratory virus infections." (PMID 36685587, 2022). "Levels of IL-4, IL-5, IL-13, and eotaxin followed the pattern established in the previous study and correlated inversely with antibody levels and directly with pulmonary eosinophilia as previously reported for other respiratory diseases." (PMID 36560488, 2022). "Eotaxins and IL-5 are involved in eosinophil-driven respiratory diseases." (PMID 24204674, 2013). "We then conducted two subgroup analyses: the first segregated the control group into healthy patients, and those with other respiratory diseases (ORD), and the second addressed three different interleukins separately (IL-6, IL-5, IL-17)." (PMID 40431146, 2025).